ZNF786 (zinc finger protein 786)
Description:
May be involved in transcriptional regulation.
Synonyms: DKFZp762I137
Tractability: PROTAC: ubiquitination databases record sites on it.
Gene: Protein-coding gene on chromosome 7 (149,069,641 to 149,090,782, reverse strand). Ensembl gene ENSG00000197362.
Subcellular location: Nucleus
Subcellular location (Human Protein Atlas): Nuclear speckles; Nucleoplasm; Nuclear bodies
Pathways (Reactome):
Gene expression (Transcription): Generic Transcription Pathway
Gene Ontology:
Molecular function: protein binding; transcription cis-regulatory region binding
Biological process: regulation of transcription by RNA polymerase II; regulation of DNA-templated transcription
Cellular component: nucleus
Genetic constraint (gnomAD): Loss-of-function variants: 56 observed, 60.01 expected, observed/expected ratio (o/e) 0.93, 90% interval 0.75 to 1.17. The upper end of that interval is the gene's LOEUF score, 1.17, which puts it in group 5 of 6, group 1 being the genes least tolerant of losing a copy. Missense variants: 1,213 observed, 1,062.9 expected, observed/expected ratio (o/e) 1.14, 90% interval 1.09 to 1.2. Synonymous variants: 485 observed, 411.03 expected, observed/expected ratio (o/e) 1.18, 90% interval 1.1 to 1.27.
Homologues: Orthologues: chimpanzee ZNF786 (98% identical), macaque ZNF786 (91% identical), dog ZNF786 (70% identical), mouse Zfp786 (64% identical), rat Zfp786 (63% identical), rabbit ZNF786 (63% identical), pig ZNF786 (55% identical), guinea pig ZNF786 (53% identical), Caenorhabditis elegans ztf-16 (10% identical), zebrafish prdm2a (10% identical), Caenorhabditis elegans sdz-12 (9% identical), Caenorhabditis elegans ehn-3 (8% identical), and 1 more. Paralogues in human: ZNF445 (28% identical), ZNF211 (26% identical), ZNF423 (19% identical), ZNF462 (17% identical), ZNF521 (17% identical), ZNF597 (15% identical), ZBTB39 (12% identical).
Diseases named in the same sentence as ZNF786 in open-access papers:
ZNF786 is named in the same sentence as 1 disease in open-access papers, as found by Europe PMC text mining. Sharing a sentence is not in itself a finding about the gene and the disease. The quoted sentences say what the papers report.
seminoma (1 paper, 2025). A radiosensitive malignant germ cell tumor found in the testis (especially undescended), and extragonadal sites (anterior mediastinum and pineal gland). "To report on hypermethylated CpG sites in seminomas compared to nonseminomas, we used an adjusted p-value of 0.01 with >10% mean difference in methylation and found a single CpG site located in chromosome 7, position 148787751, gene ZNF786, with a mean difference of 10.8." (PMID 40358182, 2025).